GPRIN2 (G protein regulated inducer of neurite outgrowth 2)
Description:
May be involved in neurite outgrowth.
Synonyms: GRIN2; KIAA0514; MGC15171
Tractability: Antibody: its Gene Ontology location is reachable by antibodies, with medium confidence; the Human Protein Atlas places it where antibodies can reach. PROTAC: its protein half-life has been measured.
Gene: Protein-coding gene on chromosome 10 (46,541,736 to 46,557,569, reverse strand). Ensembl gene ENSG00000204175.
Subcellular location (Human Protein Atlas): Microtubules; Plasma membrane; Cytokinetic bridge; Mitotic spindle
Gene Ontology:
Molecular function: protein binding
Biological process: neuron projection development
Cellular component: plasma membrane
Genetic constraint (gnomAD): Loss-of-function variants: 7 observed, 3.77 expected, observed/expected ratio (o/e) 1.86, 90% interval 0.91 to 1.96. That is too few expected variants to judge how well the gene tolerates losing a copy. Missense variants: 880 observed, 549.52 expected, observed/expected ratio (o/e) 1.6, 90% interval 1.51 to 1.69. Synonymous variants: 361 observed, 225.79 expected, observed/expected ratio (o/e) 1.6, 90% interval 1.47 to 1.74.
Homologues: Orthologues: chimpanzee GPRIN2 (97% identical), macaque GPRIN2 (95% identical), rabbit GPRIN2 (78% identical), guinea pig GPRIN2 (74% identical), mouse Gprin2 (73% identical), rat Gprin2 (72% identical). Paralogues in human: GPRIN3 (19% identical).
Diseases named in the same sentence as GPRIN2 in open-access papers:
GPRIN2 is named in the same sentence as 20 diseases in open-access papers, as found by Europe PMC text mining. Sharing a sentence is not in itself a finding about the gene and the disease. The quoted sentences say what the papers report.
Alzheimer disease (1 paper, 2017). A progressive, neurodegenerative disease characterized by loss of function and death of nerve cells in several areas of the brain leading to loss of cognitive function such as memory and language. "Based on our results, the suspected beneficial effect of 5‐HT4d on Alzheimer disease development is expected to be amplified in cells co‐expressing either GPRIN2 or GPR37." (PMID 28298427, 2017). "First, we found that GPRIN2 and GPR37 physically and functionally interact with the 5‐HT4d receptor, a promising target for Alzheimer's disease." (PMID 28298427, 2017).
esophageal squamous cell carcinoma (1 paper, 2022). Esophageal squamous cell carcinoma (ESCC) is a type of esophageal carcinoma (EC) that can affect any part of the esophagus, but is usually located in the upper or middle third. "Other exome sequencing studies have also identified a damaging germline mutation in GPRIN2 (p.A233S) in Iranian patients with familial esophageal squamous cell carcinoma (ESCC) as well as somatic mutations in melanoma samples." (PMID 36424660, 2022).
Hydrocephalus (1 paper, 2012). Hydrocephalus is an active distension of the ventricular system of the brain resulting from inadequate passage of CSF from its point of production within the cerebral ventricles to its point of absorption into the systemic circulation. "An additional sample with two events was a fetus with hydrocephalus found to have two duplication CNVs, on chromosome bands 1p33 (including the genes FAAH, DMBX1 and KNCN) and 10q11.22 (containing the genes SYT15, GPRIN2 and PPYR1), but parental samples were not available in this case." (PMID 23056206, 2012).
tumor (3 papers, 2017 to 2024). "Additionally, in vivo experiments employing the xenograft model demonstrated that GPRIN2 depletion increased tumor growth and tumor weight, while FDX1 overexpression decreased both." (PMID 38802900, 2024). "Our findings highlight FDX1 as a potential tumor suppressor in LUAD, acting through modulation of the GPRIN2/PI3K signaling pathway." (PMID 38802900, 2024). "Conversely, FDX1 overexpression led to a significant reduction in tumor growth and tumor weight in LUAD cells, an effect that was counteracted by GPRIN2 depletion." (PMID 38802900, 2024). "In that study, we found that miR-490-3p acted as a tumor-suppressive miRNA in CRC cells, and expression of its gene targets (IRAK1, FUT1, and GPRIN2) was significantly predictive of 5-year overall survival in CRC patients." (PMID 36232922, 2022). "To evaluate the impact of GPRIN2 and FDX1 on the tumorigenic potential of LUAD cells in vivo, we established a subcutaneous transplantation tumor model using FDX1-overexpressing A549 cells with or without GPRIN2 knockdown in nude mice." (PMID 38802900, 2024).
GPRIN2 also shares sentences with these, for which no sentence is quoted: bipolar disorder (2 papers); epilepsy (2); lung carcinoma (2); schizophrenia (2); autism (1); Cognitive impairment (1); focal epilepsy (1); Huntington disease (1); Intellectual disability (1); lung adenocarcinoma (1); melanoma (1); narcolepsy (1); neurodegenerative disease (1); neurological disorders (1); psychiatric disorder (1); Rett syndrome (1).